CRP (C-reactive protein)
Diseases named in the same sentence as CRP in open-access papers (continued):
Sharing a sentence is not in itself a finding about the gene and the disease.
diabetes (continued). "Although the direct pathogenic role of CRP in T2D development has been questioned recently, it is widely accepted that it is an important marker of diabetes risk as supported by a recent meta-analysis." (PMID 30210648, 2018). "A systematic review suggests that ejection fraction, sex, diabetes mellitus, previous MI, and CRP independently predicted an increased risk of cardiovascular events and can help identify patients in need of further angiographic investigation." (PMID 28599642, 2017). "We observed that the odds ratio (OR) of having diabetes associated with a unit increase of the log-transformed CRP level is 1.37 (P = 1.8 × 10−4)." (PMID 28801571, 2017). "In individuals with diabetes, CRP was associated with 54% increase in cardiovascular death and 53% greater risk of all cause mortality." (PMID 28435446, 2017). "In multivariate models, IL13 (HR = 0.77), EN-RAGE (HR = 1.23) and CRP (HR = 1.26) remained associated with incident pre-diabetes." (PMID 28258520, 2017). "The observations that increased CRP level is significantly associated with higher diabetes prevalence and elevated glucose levels are in concordant with the results of previous studies." (PMID 28801571, 2017). "Several risk factors for mortality outcomes such as BMI, smoking, arterial hypertension, diabetes mellitus, C-reactive protein and low physical activity were associated with low 25(OH)D concentrations." (PMID 28207791, 2017). "A low ABI is related to many known cardiovascular risk factors, including hypertension, diabetes, smoking, dyslipidemia, obesity, and increased serum levels of C-reactive protein." (PMID 28607554, 2017). "Multivariate Cox analysis showed that the presence of diabetes mellitus, smoking, and proteinuria and haemoglobin, Hs-CRP, IL-33, and ST2 were associated with the risk of CVE." (PMID 28614418, 2017). "Many studies associated CRP level with diabetes and glucose levels, but the association of CRP gene with these traits is unclear." (PMID 28801571, 2017). "C-reactive protein and hsCRP were associated with arterial stiffness in patients with metabolic syndrome, renal transplant, diabetes mellitus, and RA." (PMID 28912780, 2017). "High sensitivity CRP wasn’t equally associated with age and diabetes duration all known as poor glycaemic control factors." (PMID 28886725, 2017). "Elevated serum hs-CRP level was proportionally associated with increased prevalence of diabetes after adjusting for probable covariates (P for trend was <0.001 in model 2)." (PMID 28361994, 2017). "Consistent with the results of previous studies, this study showed that elevated CRP level is significantly associated with higher diabetes prevalence." (PMID 28801571, 2017). "The multivariate Cox analysis showed that the presence of diabetes mellitus, smoking, and proteinuria and levels of haemoglobin, Hs-CRP, IL-33, and ST2 were associated with the risk of CV events." (PMID 28614418, 2017). "CVD and cancer share risk factors such as obesity and diabetes mellitus and have common diagnostic biomarkers such as interleukin-6 and C-reactive protein." (PMID 29258216, 2017). "A low ABI has been related to many known cardiovascular risk factors, including hypertension, diabetes, smoking, dyslipidemia, obesity, and C-reactive protein." (PMID 28607554, 2017). "Hypertension, obesity, abdominal fat, diabetes, dyslipidemia, inflammation as reflected by high levels of C-reactive protein (CRP), are associated with CAD." (PMID 28982360, 2017). "In this study, we investigated the associations between CRP SNPs, circulating CRP, diabetes, as well as levels of fasting and 2-hour glucose based on a sample of 945 siblings collected in Taiwan, which is a population of Chinese ancestry." (PMID 28801571, 2017). "In multivariate models, IL13 (0.77), EN-RAGE (1.23) and CRP (1.26) remained associated with pre-diabetes." (PMID 28258520, 2017).
diabetes (continued). "Up to now, CRP has been associated with diabetes in populations from India24, 46, the Netherlands25, the United States26, and Greece28, but different associated polymorphisms were reported." (PMID 28801571, 2017). "In age and sex adjusted model, EN-RAGE, IL13, CFH, IL18 and CRP were associated with incident pre-diabetes." (PMID 28258520, 2017). "Subjects with high CRP levels had 2.2 and 8.1 times elevated risk of pre-diabetes and T2DM, respectively." (PMID 28716139, 2017). "Only the effect of melatonin on CRP has been described previously, in a study of diabetes-associated low-grade inflammation." (PMID 28542575, 2017). "High-sensitivity CRP, a marker of low-grade systemic inflammation, is reported as an independent risk factor of diabetes and cardiovascular disease." (PMID 28191276, 2017). "The glycated hemoglobin, even below the threshold for diagnosis of diabetes, is independently associated with obstructive sleep apnea syndrome, even after adjustment for obesity and C-reactive protein." (PMID 28767909, 2017). "Concentrations of plasma fibrinogen, PAI-1, and CRP are higher in individuals with diabetes, and many of the shared pathological changes associated with initiation and progression of atherosclerosis and diabetes are linked to insulin resistance." (PMID 28771557, 2017). "In age and sex adjusted Cox models, IL13 (HR = 0.78), EN-RAGE (1.30), CFH (1.24), IL18 (1.22) and CRP (1.32) were associated with incident pre-diabetes." (PMID 28258520, 2017). "We observed that elevated serum hs-CRP level was significantly and proportionally associated with an increased prevalence of diabetes (P for trend was <0.001) after adjusting for probable covariates (model 2)." (PMID 28361994, 2017). "Firstly, we examined the associations between CRP SNPs and CRP level and between CRP level and diabetes as well as glucose levels." (PMID 28801571, 2017). "In our studies, in health we observe some physiologic correlations such as leptin and CRP, but in diseases with sustained inflammation such as RA or diabetes mellitus, we observe loss of some physiologic and emergence of pathologic correlations." (PMID 27981248, 2016). "Of the five acute-phase proteins, subjects in the fourth compared to the first quartile of orosomucoid, haptoglobin and CRP, respectively, had significantly higher risk of incidence of diabetes in the first model." (PMID 27581604, 2016). "Poorer lung function was associated with several adverse CV risk factors including smoking, physical inactivity, diabetes, inflammation (CRP) and cardiac dysfunction (NT-proBNP, cTnT)." (PMID 26811343, 2016). "In conclusion, this study demonstrated that there are associations between orosomucoid, haptoglobin, and CRP and the risk of incident diabetes." (PMID 27581604, 2016). "We found that ejection fraction, sex, diabetes mellitus, previous MI, and CRP independently predicted an increased risk during a cumulative five-year follow-up." (PMID 27239372, 2016). "The study demonstrated that there are associations between orosomucoid, haptoglobin and CRP and the risk of incidence of diabetes." (PMID 27581604, 2016). "High age, diabetes and CRP have been recognized as risk factors for conversion by other studies as well." (PMID 27891173, 2016). "Recently, another ELSA study demonstrated that those with both elevated depressive symptoms and high CRP levels were also at an increased risk of developing diabetes." (PMID 27227974, 2016). "This is in accordance with findings from a case-control study by McMillan, which showed increased levels of haptoglobin, orosomucoid, and CRP in association with diabetes and glucose intolerance." (PMID 27581604, 2016). "A previous study of non-GFR factors associated with cystatin C concentrations found diabetes mellitus, increased C-reactive protein, increased white blood cell count, and decreased albumin concentrations to be independently predictive of increased cystatin C." (PMID 27293926, 2016).
diabetes (continued). "Orosomucoid, haptoglobin, and CRP showed a significant increased risk of diabetes after adjustment for potential confounders." (PMID 27581604, 2016). "Metabolically unhealthy subjects showed significantly higher levels of CRP compared with their metabolically healthy counterparts, consistent with the known role of systemic inflammation in the risk of diabetes." (PMID 26881247, 2016). "In population-based studies, such as the Multi-Ethnic Study of Atherosclerosis, Atherosclerosis Risk in Communities and West of Scotland Coronary Prevention Study (WOSCOPS), inflammatory markers (e.g. IL-6, CRP), are strongly associated with diabetes risk." (PMID 27666719, 2016). "The present study showed that pre-operative GDF-15 levels in patients undergoing OPCAB were positively associated with age, hypertension, diabetes, Scr, EuroSCOREII, NT-proBNP, hemoglobin, and plasma CRP levels." (PMID 27311391, 2016). "The findings of this study also suggest an increased level of systemic inflammation as risk of diabetes increases, indicated by higher levels of circulating C-reactive protein in the higher HbA1c categories." (PMID 26989697, 2016). "On-admission fibrinogen ranged between 3.1 and 24.3 μmol/L and higher values were independently associated with older age (p = 0.002), higher C-reactive protein (p < 0.001), history of diabetes (p = 0.038) and history of heart failure (p = 0.020)." (PMID 27576312, 2016). "Incidence of CKD was significantly associated with age, sex, eGFR, CRP subgroups, hypertension, diabetes mellitus, overweight, NSAIDs use at baseline for this study." (PMID 27537204, 2016). "A recent meta-analysis confirms the consistent dose-response relationships between IL-6, CRP and diabetes risk." (PMID 27666719, 2016). "Among the leukocyte subpopulations, only neutrophils remained significantly associated with incidence of diabetes after adjustment for CRP (HR: 1.39; 1.08–1.78, P for trend 0.022), S3 Table." (PMID 26891449, 2016). "Obesity and high body fat are associated with diabetes and abnormal glucose metabolism, as well as with elevated circulating levels of CRP and other pro-inflammatory cytokines." (PMID 25994228, 2015). "Genetic variation and levels of CRP and incidence of diabetes especially risk of developing type 2 diabetes mellitus have been studies." (PMID 26273663, 2015). "Here we found that elevated C-reactive protein, and older age remained independently associated with diabetes in addition to abnormal waist-to-hip ratios." (PMID 26186342, 2015). "Older age, a higher CRP, a lower albumin concentration, a history of cardiovascular disease and diabetes mellitus also showed an association." (PMID 25823004, 2015). "Our CRP results are consistent with a multitude of studies showing a linear relationship between CRP and cardiovascular risk, including the risk of progression to diabetes mellitus." (PMID 26549941, 2015). "It has recently been shown that low 1,25(OH)2D levels are independently associated not only with poor kidney function but also with low 25OHD levels, high CRP levels, diabetes mellitus and high values of the cardio-surgical risk marker EuroSCORE." (PMID 25885271, 2015). "CRP levels have an association with smoking, obesity, triglycerides, diabetes, and periodontal disease." (PMID 26346216, 2015). "CRP is generally accepted as a biomarker for chronic low-grade inflammation usually observed in association with obesity, diabetes, or cardiovascular diseases." (PMID 26489667, 2015). "Asp299Gly polymorphism in the TLR4 gene, which impairs inflammatory responses, is associated with reduced vascular inflammation, assessed by C-reactive protein and a decreased risk for coronary artery disease and diabetes." (PMID 26030867, 2015). "This study examined the possible mediating effects of adiponectin, leptin, and C-reactive protein (CRP) concentrations on the smoking-diabetes association." (PMID 25400076, 2015).
diabetes (continued). "In conclusion, CR in ischemic stroke patients is associated with several independent risk factors, including diabetes, hs-CRP-increased use of CCBs, and use of β-blockers." (PMID 25452814, 2015). "Recent research suggests that patients with elevated basal levels of CRP are at increased risk of diabetes, hypertension, and cardiovascular disease." (PMID 25159658, 2015). "A recent meta-analysis of perspective studies identified the two inflammatory markers IL-6 and C-reactive protein (CRP) as significantly associated with diabetes, with an increased risk of 26% associated with elevated CRP, and 31% due to elevated IL-6 levels." (PMID 26783955, 2015). "Elevated CRP levels and risk of diabetes have mainly been associated with long-term exposure to air pollution." (PMID 25890359, 2015). "In the general population, high CRP levels correlate with risk of vascular death and cancer death, as well as the development of diabetes mellitus." (PMID 26218286, 2015). "Studies have also shown an association of CRP levels with CAD risk factors like diabetes and hypertension." (PMID 25822970, 2015). "Inflammatory markers, such as CRP were not considered as response variables in our analysis due to the high prevalence of infectious diseases, complicating the interpretation of CRP as a risk factor for diabetes." (PMID 26198248, 2015). "Serum levels of TNF-α and IL-6 were measured by enzyme-linked immunosorbent assay and CRP by nephelometry by using the proper commercial kits in 30 patients with diabetes and periodontal disease, and also in a control group of 30 healthy subjects." (PMID 26644840, 2015). "Nevertheless, CRP genotype polymorphisms are associated with a small difference (about 60 %) in serum CRP levels, and of insufficient magnitude for an association with incident diabetes to be detected." (PMID 25994228, 2015). "Additional adjustment for HOMA2-IR, only attenuated VAT associations with clinical and subclinical CHD; associations remained significant for diabetes, HbA1c and CRP." (PMID 24862429, 2014). "Old age, smoking, alcoholic drinking, hypertension, diabetes mellitus, hyperlipidemia, elevated C-reactive protein are all considered associated with osteoporotic fractures." (PMID 24529197, 2014). "The levels of adiponectin have been found to be inversely associated with marker of inflammation CRP in patients with diabetes and coronary atherosclerosis." (PMID 25183967, 2014). "C-reactive protein (CRP) is one of the most significant acute-phase proteins in humans and has been associated with an increased risk in the development of diabetes." (PMID 25226365, 2014). "In the first model, adjusted for age and sex, severity of sleep disturbances was associated with CHD, myocardial infarction, heart failure, diabetes, dyslipidemia, and elevated C-reactive protein." (PMID 25093413, 2014). "In response to inflammatory signals, the liver produces the classic short pentraxin C-reactive protein (CRP), which strongly associates with cardiometabolic disorders such as obesity, metabolic syndrome, diabetes mellitus, and atherosclerosis." (PMID 24705587, 2014). "Diabetes, smoking, obesity and insulin resistance are all been associated with small increases in CRP-levels as assessed by high sensitivity methods." (PMID 24681553, 2014). "This association was attenuated when adjusted for diabetes status, BMI, lipids, blood pressure and eGFR (model 2), and was abolished with adjustment for further covariates including CRP (model 3)." (PMID 24505486, 2014). "Diabetes prevalence, mean/median waist-to-hip ratio and circulating C-reactive protein levels were negatively associated with HDL-C levels (all P < 0.05)." (PMID 24888391, 2014). "We found that increased adiposity measured by both body mass index and waist circumference was associated with increased C-reactive protein (CRP) and decreased vitamin C after adjusting for age, duration and treatment of diabetes (p < 0.05)." (PMID 25375631, 2014).
diabetes (continued). "In a large cohort study, the prevalence of retinopathy was positively associated with CRP levels in patients with diabetes." (PMID 24905410, 2014). "Our data showed that pre-operative GDF-15 levels in patients undergoing bypass surgery were positively associated with age, a history of diabetes, chronic renal failure, high NT-proBNP and plasma CRP levels." (PMID 25171167, 2014). "There were significant independent associations between GDF-15 levels and current smoking, diabetes mellitus, and biomarkers indicating renal dysfunction (cystatin C), cardiac dysfunction (NT-proBNP, troponin T) and also inflammatory activity (CRP)." (PMID 24312445, 2013). "The following CVD risk factor outcomes were used: hypertension, diabetes, total and high density lipoprotein cholesterol, glycated haemoglobin, fibrinogen, C-reactive protein and Framingham risk score." (PMID 23844088, 2013). "In this high risk Aboriginal population, SBP, serum albumin (inverse association), uric acid, CRP, diabetes were significantly associated with albuminuria (p value for GGT was 0.054)." (PMID 23947772, 2013). "Elevated CRP levels are also associated with systemic diseases including cardiovascular disease, metabolic disease and diabetes." (PMID 24147095, 2013). "The positive association between CRP and BMI is widely known in healthy controls and other populations (diabetes, hypertension)." (PMID 23826157, 2013). "In the analysis of relevant risk factors, hypertension, diabetes, a body temperature of >37.5°C and hs-CRP were correlated with progressive stroke." (PMID 23737893, 2013). "Elevated CRP has been recently shown in a systematic review and meta-analysis to be associated with an ~30% increase in the risk of diabetes development." (PMID 24155956, 2013). "In this context, cardiovascular disease and diabetes are both associated with elevated levels of inflammatory biomarkers including cytokines and C-reactive protein (CRP)." (PMID 23642086, 2013). "We found an elevated CRP level and diabetes mellitus were significantly associated with poor outcome in patients with BAD and its subgroup of PPA, while only the elevated CRP level had a relevance to that in the LSA group." (PMID 24039853, 2013). "CRP is a well known serum marker of chronic low-grade inflammation and has been associated with diabetes, hypertension and CVDs." (PMID 23342952, 2013). "Initial studies indicated an association between elevated CRP levels and frailty after exclusion of CV diseases and diabetes." (PMID 24244750, 2013). "Elevated Hcy (P = 0.004) and increased CRP (P = 0.025) were associated with progression in patients with BAD, and CRP (p = 0.006) and diabetes mellitus (p = 0.011) were found to be associated with poor outcome in patients with BAD." (PMID 24039853, 2013). "Major periodontal risk factors were recorded (age, gender, diabetes and smoking status), as well as plasma levels of inflammatory markers (CRP, orosomucoid, IL-6) and adipokines (adiponectin, leptin)." (PMID 23526947, 2013). "Adiponectin is known to play a protective role in the development of insulin resistance and diabetes, both of which are positively associated with elevated levels of CRP and IL-6." (PMID 23984329, 2013). "CRP has been reported to be a novel cardiovascular risk factor, and we have reported that it is independently associated with the development of diabetes in this Aboriginal cohort." (PMID 23947772, 2013). "The normalization of CRP was delayed by a postoperative reaction and the effects of an underlying disease such as cancer, diabetes and rheumatoid arthritis." (PMID 22806173, 2012). "CRP is associated with cardiovascular disease, type 2 diabetes mellitus, and cancer, and identification of the factors associated with serum CRP concentration is important to their prevention." (PMID 23110638, 2012).